LEP (leptin)
Diseases named in the same sentence as LEP in open-access papers (continued):
Sharing a sentence is not in itself a finding about the gene and the disease.
liver disease (45 papers, 2004 to 2026). "In this large, unselected screening cohort from Central Europe, we observed a robust, dose-dependent association between circulating leptin levels and steatotic liver disease." (PMID 40956476, 2025). "We enrolled 160 critically ill patients with liver disease and 20 healthy individuals to measure serum leptin concentrations as a potential biomarker for diagnostic and prognostic purposes." (PMID 38927377, 2024). "Leptin, a hormone that is predominantly produced by adipose tissue, is closely associated with various liver diseases." (PMID 34830465, 2021). "Using a comprehensive panel of circulating organokines, including fibroblast growth factor (FGF) 19, FGF21, adiponectin, galectin-3, irisin, and leptin, along with choline metabolites, we characterized metabolic signaling patterns associated with liver disease severity." (PMID 40943431, 2025). "Its use however remains limited, particularly in the setting of ICI and cancer therapy, with possible associations of leptin therapy with immune effects on T cells, as well as unclear relationships with T cell lymphoma and activation of autoimmune renal or hepatic disease." (PMID 41476924, 2025). "In order to determine whether LEPTIN deficiency altered clinical indicators of liver disease as observed in obese patients, blood was collected from pigs at 4-, 12- and 18-months of age." (PMID 37705071, 2023). "Compelling evidence reported that sleep insufficiency had significant effects including reduction of leptin and elevation of ghrelin, which might predispose to liver diseases by means of proinflammatory markers and stress response." (PMID 36568745, 2022). "In addition, a growing body of recent evidence has suggested that leptin signaling is also implicated in the development and progression of various types of liver diseases via multiple mechanisms." (PMID 34830465, 2021). "Clinical studies have indicated that increased levels of leptin were significantly associated with the amount of alcohol consumed by active drinkers throughout their lives, regardless of nutritional status or the presence of compensated liver disease." (PMID 32265847, 2020). "Moreover, the procarcinogenic roles of leptin and associated liver diseases (i.e., NAFLD) have been linked to the promotion of CRC cell invasiveness via the activation of the MAPK signaling pathway." (PMID 33276422, 2020). "There were significant differences in body mass index (P < .0001), SFMI (P < .0001), L3 skeletal muscle index (P < .0001), platelet count (P = 0.003), hemoglobin A1c (P < .0001), triglycerides (P = 0.004), serum leptin (P = 0.043), and underlying liver disease (P < .0001) between the groups." (PMID 29581826, 2018). "We therefore conducted a comprehensive analysis in a large, representative Central European screening cohort to examine the association between leptin levels, RLD status, and steatotic liver disease." (PMID 40956476, 2025). "Human liver samples also displayed a significant increase in leptin expression as liver disease progressed, which was the highest in HCC samples." (PMID 34680297, 2021). "Although leptin signaling is widely known to play important roles in various liver diseases by modulating different types of liver cells, there is limited knowledge regarding the cytotoxic effect of leptin in hepatocytes." (PMID 34830465, 2021). "Serum LEP level in patients with liver diseases and HCC was categorized in the Child-Pugh classification." (PMID 33369452, 2020). "The mean values of serum LEP level were 10.1, 7.2 and 6 ng/ml in class A, B and C of patients with liver diseases or HCC respectively according to the Child-Pugh classification." (PMID 33369452, 2020). "Serum LEP level was reduced in patients with liver diseases or HCC in class C than that in patients in class A." (PMID 33369452, 2020).
liver disease (continued). "In the present study, it was found that serum leptin level was slightly reduced in patients with liver diseases or HCC in Child- C than that in patients in Child-A." (PMID 33369452, 2020). "In our analyses of human liver disease samples, we found that there were two groups of patients with inflammation: those with either low or high leptin expression." (PMID 30718259, 2019). "We also found that leptin expression progressively increased during human liver disease progression." (PMID 30718259, 2019). "The intensive 16-week lifestyle intervention program decreased body weight, portal hypertension and systemic leptin levels." (PMID 28661458, 2017). "A separate study describes a transient increase of serum leptin in early stages of liver disease, which normalize in those patients with advanced disease." (PMID 28661458, 2017). "Increased serum leptin levels have also been correlated with severity of liver disease i.e., the amount of inflammation and fibrosis." (PMID 28758929, 2017). "The level of leptin in our cohort was assessed during an acute phase of liver disease with coexistence of signs of hypermetabolism and systemic inflammatory activation." (PMID 24259947, 2013). "The role of leptin in the course of liver disease due to chronic viral hepatitis (CVH) remains controversial." (PMID 17540037, 2007). "The behavior of leptin concentrations in the course of liver disease due to HBV and HCV infection is still under investigation." (PMID 17540037, 2007). "Serum leptin levels increase in advanced liver disease independently of gender, body composition and viral etiologic factor in post-hepatitis cirrhosis." (PMID 15387890, 2004). "Serum leptin levels increase in advanced liver disease independently of gender, body composition in posthepatitic cirrhosis." (PMID 15387890, 2004). "Additionally, imbalances in adipokines, such as decreased adiponectin and elevated leptin, further disrupt metabolism and accelerate liver disease progression." (PMID 40364004, 2025). "Due to expanded and inflamed abnormal adipocytes, increased adipocytokines such as TNF-α and leptin and decreased adiponectin secretion could contribute to apoptosis and necrosis in hepatocytes, progressing to liver disease." (PMID 35251036, 2022). "The correlation of leptin levels with liver diseases, such as cirrhosis and fibrosis, supports that leptin may mediate the pernicious influence of abnormal adipose tissue on the liver." (PMID 35379822, 2022). "In liver disease, glucose metabolism shifts from the liver to muscle and adipose tissue, which stimulates mitochondrial oxidative stress and drives the production of proinflammatory adipokines, e.g., leptin, tumor necrosis factors-alpha and interleukin-6." (PMID 35743539, 2022). "Increased serum leptin levels correlate with severity of liver disease in NAFLD." (PMID 31947953, 2020). "However, despite the large body of evidence implicating leptin in the overall scheme of hepatic diseases, the question is, friend or foe?" (PMID 33316927, 2020). "Serum LEP level and LEPR Q223R gene polymorphism were determined in 300 patients with liver disease categorized equally into five groups’ healthy volunteers, patients with hepatitis C (HCV), patients with non-alcoholic steatohepatitis (NASH), liver cirrhosis and HCC." (PMID 33369452, 2020). "However, increased serum leptin levels have been correlated with the amount of inflammation and fibrosis in liver diseases." (PMID 30818874, 2019). "Hence, leptin signaling is likely universal during liver disease progression from fatty liver to carcinogenesis." (PMID 30718259, 2019). "In addition to TLR4 and MCP-1, leptin has also been known to play an active role in the progression of liver diseases." (PMID 26484872, 2015). "In addition to MCP-1, leptin, a proinflammatory adipokine, has been known to play an active role in the progression of liver diseases." (PMID 26484872, 2015).
liver disease (continued). "Longitudinal studies incorporating diverse populations are needed to clarify whether leptin trajectories predict hepatic disease progression and to determine whether population-specific reference ranges improve the identification of clinically meaningful leptin deficiency." (PMID 40956476, 2025). "Moreover, inflammatory cytokines like tumor necrosis factor-alpha and adipokines like leptin, which are often elevated in NAFLD, have been implicated in the progression of liver disease and also exert biological effects in other tissues and conditions, including COPD34–36." (PMID 38734742, 2024). "This study aims at contributing to our understanding of the role of leptin,vitamin D, APRI, and FIB-4 in the progression of liver disease." (PMID 41721256, 2026). "Leptin, a hormone that regulates energy homeostasis, was identified to be involved in HCC-induced muscle-wasting as well as in human liver disease." (PMID 34680297, 2021). "In alcoholic patients, leptin levels have been reported to be increased, decreased, or unchanged, and serum leptin levels were not altered by either alcohol withdrawal or the severity of liver disease." (PMID 33167521, 2020). "First, it is possible that the elevation of leptin levels reflects an effect of adiposity-driven dysregulation of the adipo-insular axis regardless of liver disease." (PMID 32092909, 2020). "In alcoholic patients, leptin has been reported to be increased, decreased or unchanged, and serum leptin was also not altered by either alcohol withdrawal for 15 days or the severity of liver disease." (PMID 28212318, 2017). "In addition, leptin can induce expression of TGF-β and CTGF expression in Kupffer cells thereby promoting the progression of hepatic disease." (PMID 26779021, 2015). "Along with cirrhotic complications, another small study including prospectively 94 NAFLD non-cirrhotic patients, showed the occurrence of PVT in 8% of the cohort even without advance liver disease, especially in obese subjects and those with increased leptin levels." (PMID 38066387, 2024). "Interestingly, the potential driver oncogenes in these human samples could be variable but the leptin level increased in the majority of the samples during liver disease progression, indicating that upregulation of leptin is not specific to a particular oncogene." (PMID 30718259, 2019).
Arthritis (44 papers, 2005 to 2025). Inflammation of a joint. "We did not observe an association between serum levels of adiponectin, leptin, chemerin, resistin, or omentin and the subsequent development of clinically manifest arthritis." (PMID 26670468, 2015). "Adipokines leptin, adiponectin and resistin have recently been associated with inflammation and cartilage destruction in arthritis." (PMID 25333960, 2014). "In experimental models of arthritis, leptin deficient mice showed a milder form of antigen-induced arthritis associated with the reduction of IFN-γ production and the increase in IL-10 secretion by in vitro reactivated lymph node cells." (PMID 24799765, 2014). "In antigen-induced arthritis models, leptin-deficient mice developed less severe arthritis with lower mRNA levels of proinflammatory cytokines compared with control mice and had reduced inflammation." (PMID 24376307, 2013). "Treatment with metformin, alendronate, and their combination caused a significant decrease of leptin serum concentration in the chronic phase of arthritis, suggesting an advantageous effect via the restriction of both inflammation and remodeling processes in the affected joints." (PMID 34440221, 2021). "Regarding the severity of arthritis, the most important finding of this investigation is the reduced arthrogram score associated with a profound decrease of circulating leptin and a marked increase of circulating ghrelin and corticosterone levels due to the food restriction." (PMID 20953376, 2010). "The severity of antigen-induced arthritis is decreased in leptin-deficient ob/ob mice." (PMID 16277669, 2005). "According to the literature, leptin contributes to arthritis pathogenesis by affecting synoviocyte function and cytokine production, and therefore, promoting inflammation." (PMID 40018036, 2025). "Leptin and adiponectin, being important adipokines, not only regulate insulin sensitivity and lipid metabolism but also contribute to the occurrence of arthritis by modulating inflammatory and immune responses." (PMID 38481325, 2024). "In another study, leptin injection into mice with collagen-induced arthritis exacerbated joint inflammation and resulted in joint damage." (PMID 35346353, 2022). "Leptin increased the severity of K/BxN arthritis in mice, while administration of leptin receptor antagonist (Allo-aca) attenuated the disease severity." (PMID 35270000, 2022). "Treatment with metformin, alendronate, and their combination decreased serum concentrations of leptin and resistin in the chronic phase of arthritis." (PMID 34440221, 2021). "In collagen-induced arthritis mouse model, articular injection of leptin (5 μg) increased the number of Th17 in the joint tissue, resulting in exacerbating joint inflammation, and consequently early onset of arthritis and increased disease severity." (PMID 29910742, 2018). "Accordingly, injection of leptin (5 μg) into the knee joint of collagen-immunized mice augmented arthritis severity, accompanied by elevated synovial hyperplasia and joint damage through enhancement of Th17 cell response." (PMID 29910742, 2018). "In preclinical setting, both the leptin deficient and leptin receptor deficient mice exhibited a delayed resolution of arthritis, and leptin supplementation was reported to ameliorate arthritis." (PMID 27041823, 2016). "In mice with antigen-induced arthritis, impaired leptin signaling via leptin or leptin-receptor deletion attenuates arthritis severity, demonstrating that leptin plays a direct role in RA progression." (PMID 23922673, 2013). "Our data show that fenofibrate administration ameliorates the inhibitory effect of arthritis on serum leptin and adiponectin." (PMID 23781298, 2012). "The most studied adipokine in the pathophysiology of arthritis is leptin, which has been proven to have proinflammatory and catabolic roles in OA." (PMID 22077999, 2011).
Arthritis (continued). "Leptin is an adipokine regulating energy balance, and it has recently been related also to arthritis and inflammation as a proinflammatory factor." (PMID 19688109, 2009). "Our results and literature data show, that TRF prevents the elevating effect of HF diet on leptin production, which could contribute to the reduced inflammatory phenotype observed in our K/BxN serum-transfer arthritis model." (PMID 40018036, 2025). "Thus, MetS and the dysregulated secretion of pro-inflammatory adipokines like leptin, adiponectin, and lipocalin-2 affect the immune system, MetS, and arthritis." (PMID 39407941, 2024). "Upon injecting leptin into the knee joint of collagen-immunised mice, the onset of arthritis accelerated significantly, resulting in exacerbation of clinical symptoms and a notable increase in synovial hyperplasia, joint degeneration, and abundance of Th17 cells in the joint tissue." (PMID 38001998, 2023). "Experimental animal models of arthritis had demonstrated the leptin action in joint inflammation." (PMID 29910742, 2018). "This suggests that leptin is associated with MetS but not directly with arthritis, although a marked increase in plasma levels of leptin in patients with RA was noted." (PMID 24741591, 2014). "Finally a local overexpression of several cytokines/adipocytokines poorly described in arthritis (IL-13, IL-18, leptin) was observed." (PMID 22414623, 2012). "Arthritis also decreased serum concentration of leptin (P<0.01)." (PMID 23781298, 2012). "Sera leptin decreased significantly after 3 days and then returned to its original high level, whereas in SF, an increase was observed after 14 days, indicating the potential role of this adipokine in arthritis chronicity and bone degradation in the long term." (PMID 22414623, 2012). "In addition, food restriction during arthritis resulted in significantly lower levels of leptin compared to the other dietary modulated arthritic rats." (PMID 20953376, 2010). "In addition to arthritis, these hTNFα transgenic mice demonstrated major alterations in body composition, metabolic rate, leptin levels, response to a high-fat diet, bone mineral density and content, impaired fertility and male sexual function." (PMID 18070349, 2007). "In addition, leptin regulates not only humoral but also cellular immune responses in antigen-induced arthritis models." (PMID 15899045, 2005). "In contrast, in zymosan-induced arthritis (ZIA), a model of proliferative arthritis, the resolution of joints inflammation was delayed in ob/ob and db/db mice and the severity of articular damage, as indicated by the histopathological scores, was higher in leptin-deficient mice compared to controls." (PMID 35270000, 2022). "The large reduction of leptin levels by TRF raises the possibility, that - as a cytokine - it played an important role in regulating arthritis development in our experiments." (PMID 40018036, 2025). "In another model of arthritis induced by collagen (CIA) in high-fat-diet-induced obese mice, mice developed peripheral leptin resistance and exhibited decreased disease severity and collagen-induced inflammation." (PMID 35270000, 2022). "Leptin intraarticular injection into CIA mice increased Th17 cells in joint tissue and exacerbated arthritis symptoms and synovial hyperplasia leading to enhanced cartilage degradation and bone erosion." (PMID 35270000, 2022). "Regarding arthritis, most studies have focused on the involvement of HDAC3 in leptin-induced arthritis and synovitis in rheumatic arthritis, caused by metabolic dysfunction and autoimmunity dysfunction, respectively." (PMID 31481898, 2019). "Our results showed that leptin heightened OSM expression by downregulating miR-93 through the Akt signaling pathway in osteoblasts, suggesting leptin as a novel target in arthritis treatment." (PMID 25198901, 2014). "Adjuvant-induced arthritis in rats decreases WAT mass, serum leptin, and adiponectin as well as its expression in the adipose tissue." (PMID 23781298, 2012).